LINC01697 (long independently transcribed non-coding RNA 1697)
Gene: Long non-coding RNA gene on chromosome 21 (28,048,404 to 28,137,611, forward strand). Ensembl gene ENSG00000232079.
Diseases named in the same sentence as LINC01697 in open-access papers:
LINC01697 is named in the same sentence as 4 diseases in open-access papers, as found by Europe PMC text mining. Sharing a sentence is not in itself a finding about the gene and the disease. The quoted sentences say what the papers report.
gastric cancer (1 paper, 2021). A primary or metastatic malignant neoplasm involving the stomach. "Compared to normal GES-1 cells, the relative mRNA expression levels of LINC01644 and LINC01697 significantly increased in gastric cancer cells, including SGC-7901, BGC-823, and HGC-27 (P < 0.05)." (PMID 34603561, 2021).
lung adenocarcinoma (1 paper, 2023). A carcinoma that arises from the lung and is characterized by the presence of malignant glandular epithelial cells. "For example, LINC01697 has a diagnostic and prognostic function in lung adenocarcinoma and oral squamous cell carcinoma." (PMID 36992704, 2023).
tumour (1 paper, 2021). "Subsequently, the results of the CCK8 assay show that knockdown of LINC01644 and LINC01697 inhibited tumour cell proliferation of SGC-7901 cells." (PMID 34603561, 2021).
LINC01697 also shares sentences with these, for which no sentence is quoted: oral squamous cell carcinoma (1 paper).